TLR2 (toll like receptor 2)
Diseases named in the same sentence as TLR2 in open-access papers (continued):
Sharing a sentence is not in itself a finding about the gene and the disease.
infection (continued). "While MyD88−/− mice developed larger and prolonged lesions compared to those in control mice, the lack of TLR2 resulted in enhanced DC activation and increased IL-12 production after infection." (PMID 22523644, 2012). "We evaluated TLR2/1L-induced innate immune cytokines e.g. TNF-α, IL-1β, IL-6, IL-23 and IL-12, known to be critical players in the control of Mtb infection, and chemokines such as Gro-α and IL-8 that are required for cell recruitment to the site of infection." (PMID 22866178, 2012). "Here again, TLR2−/− mice are indistinguishable from control mice in the ability to restrict systemic infection." (PMID 22973560, 2012). "TLR2 stimulation of Langherhan cells, which are the initial targets of HIV infection following sexual exposure, results in enhanced infection of these cells and subsequent trans-infection of T cells." (PMID 22844428, 2012). "The authors observed upregulation of TLR2 and TLR4 from day 1 to day 28 postinfection, and increased expression correlated with higher mRNA levels for TNFα, IL-17, IL-10, and TGFβ during early infection." (PMID 22523644, 2012). "As a consequence, our data do not exclude a protective role for TLR2 in asplenic animals after infection with a low nonlethal dose of S. pneumoniae." (PMID 22721450, 2012). "Therefore, to further elicit the role of TLR2, in the present study we compared the host response in splenectomized TLR2KO and WT mice after infection with encapsulated (serotype 2 and 3) S. pneumoniae via the airways." (PMID 22721450, 2012). "A lack of control in the absence of TLR2 results in enhanced infection that drives greater TLR4-mediated inflammatory responses, including maintenance of high levels of NK cells, neutrophils, DCs and T-cells." (PMID 22724018, 2012). "There were no changes in Tlr2 of B6 mice, and the upregulated expression of Tnf of B6 mice was significant lower than that of A/J mice after infection with SS2." (PMID 22384161, 2012). "In a murine model of staphylococcal cutaneous infection, TLR2−/− mice have larger lesions than wild-type mice although neutrophil recruitment was not impaired on day 1 post-infection." (PMID 23316483, 2012). "The decreased infection of HSV-1 at all time points in CD200R1−/− MEFs as well as macrophages indicates that the situation is more complex than simply the suppression of a virus-toxic metabolite such as NO, which can be driven or amplified by TLR2." (PMID 23082204, 2012). "We first assessed the impact of the absence of TLR2 and 4 on neonatal growth and clinical features during infection." (PMID 22724018, 2012). "Here, the infection with P. yoelii 17XL or 17XNL induced the expression of TLR2, but not TLR4 and TLR9, on murine macrophages in the present study." (PMID 22463100, 2012). "We found that poly(I∶C)- and LPS-stimulation of MDMs abrogated infection by CCR5-using, macrophage-tropic HIV-1, and by vesicular stomatitis virus glycoprotein-pseudotyped HIV-1 virions, while TLR2, TLR7 or TLR9 agonists only partially reduced infection to varying extent." (PMID 23028330, 2012). "No studies to date have monitored the course of infection in the absence of TLR2 following respiratory challenge with C. muridarum." (PMID 21695078, 2011). "Quantitative real-time PCR of TLR2 mRNA in retinas demonstrated no change in expression during infection." (PMID 22163046, 2011). "To investigate the role of TLR-2 and TLR-5 during infection in more detail and to clearly distinguish this from signalling induced by the cagPAI-dependent injection of peptidoglycan and CagA, we were screening for a cell model system in which T4SS effectors cannot be injected." (PMID 21573018, 2011). "Finally, after S. suis invasion of the central nervous system, transcriptional activation of TLR2, TLR3 and CD14 has been observed in a mouse model of infection." (PMID 21635729, 2011).
infection (continued). "Neutrophils and monocytes were recruited to the spleen of TLR2−/− mice, but not to control mice, as the infection by the low virulence PCA2 strain was quickly stopped in wild-type animals." (PMID 21935459, 2011). "Taken together, we propose a model in which macrophages integrate signals from the spatiotemporally separated TLR2 signaling pathway and AIM2 inflammasome complex during infection in order to mount an appropriate innate immune response against invading bacteria." (PMID 21698237, 2011). "In untreated rabbits, most of these genes were progressively induced by Mtb infection from 4 to 8 weeks, and many had reached a plateau (IFN-γ, IL13, IL6, MIF, CCL4, NFκB, APRIL, TLR2, RAB7 and LAMP2) or were even reduced (IL10, CXCR3, GMCSF and PI3K3) by 12 weeks post-infection." (PMID 21949656, 2011). "While the bacterial burden and course of infection in the genital tract is unchanged in the absence of TLR2, expression of proinflammatory cytokines and chemokines in the genital tract is reduced, and upper tract pathology is diminished or absent." (PMID 21695078, 2011). "High expression levels of lymphocyte activation marker (CD38), TLR2, macrophage inflammatory protein (CCL4) and osteopontin (SPP1) at 4 weeks that was sustained until 16 weeks of infection suggested an early and robust inflammation in the lungs in association with progression of the disease." (PMID 22645653, 2011). "Interestingly, both synergy and co-operation between TLR2 and TLR9 have been observed in response to infection resulting in heightened Th1-like responses." (PMID 21695103, 2011). "If both TLR2 and TLR4 respond similarly in the eye to infection with B. cereus, this may account for the unusually robust inflammation observed during this disease." (PMID 22163046, 2011). "Because TLR2 activates the inflammatory state of PMNs in infection and unrestrained inflammation occurred in condition of defective S100B/RAGE axis, we hypothesized that the S100B/RAGE axis may inhibit TLR2/MyD88–driven inflammation to the fungus." (PMID 21423669, 2011). "Utilizing our previously published protocol for live infection induced antigen sensitization, WT, TLR2−/−, TLR4−/−, and TRIF−/− mice were infected with 5×105 IFU of CP, sensitized with HSA for three days (beginning 5 days after infection), and then challenged with HSA." (PMID 21695198, 2011). "At 6 h post-infection, soon after F. novicida starts to replicate in the cytosol, 12% of wild-type macrophages were dead while no death was detectable in TLR2−/− cells." (PMID 21698237, 2011). "CAPE-treated wild-type and TLR2−/− macrophages did not undergo cell death or secrete IL-18 after F. novicida infection." (PMID 21698237, 2011). "At 6 h post-infection, we detected the processed p20 subunit of caspase-1 in lysates from infected wild-type, but not TLR2−/− macrophages." (PMID 21698237, 2011). "We focussed on TLR1, TLR2, and TLR4, because these receptors alone or in combination recognise the bacterial products LTA or LPS which might be present at the site of infection." (PMID 21151520, 2010). "We found an early up-regulation of Ppargc1a and Ppargc1b post-infection (at 6 h) in WT mice, but the expression of both genes was concordantly dysregulated in TLR2−/− mice (no increase at 6 h) and in TLR4−/− mice (amplified at 6 h)." (PMID 20657826, 2010). "TLR2 recognition of viable mycoplasma species leads to stimulation of innate immune mechanisms controlling the level of infection in lungs, but these receptors have no apparent effect in nasal passages." (PMID 20505832, 2010). "Three days post-infection, TLR2−/− mice had higher M. pulmonis numbers in lungs, but not in nasal passages." (PMID 20505832, 2010). "Collectively, our data suggest that TLR2 activation leads to SPLUNC1 up-regulation, which in turn may dampen TLR2 signaling, leading to airway homeostasis following an infection or exposure to environmental stimuli." (PMID 21054862, 2010).
infection (continued). "In support, HEK cells expressing TLR2 responded to M. pulmonis infection, and TLR2−/− dendritic cells did not respond to infection whereas wild type cells produced significant cytokine responses." (PMID 20505832, 2010). "Purified NK cells from WT or TLR2−/− mice were co-cultured in vitro with WT CD11c+ DCs in the presence of a blocking anti-NKG2D antibody or a blocking NKp46-Fc fusion protein, followed by infection with VV, the activation of NK cells was analyzed 24 h later." (PMID 20300608, 2010). "Together, these results clearly indicate that deficiency in TLR2, TLR4, TLR9 or even MyD88 expression does not impair CD8+ T cell effector responses during infection with T. cruzi." (PMID 20442858, 2010). "Our studies demonstrate that TLR2 signaling via MyD88 plays an important role in innate immune responses to F. tularensis infection in vivo regardless of the route of infection and regardless of the subspecies of F. tularensis." (PMID 19936231, 2009). "Recent in vivo studies have indicated that TLR2 is critical for protection against intranasal F. tularensis infection but not against intradermal infection." (PMID 19936231, 2009). "Confirming the absence of MyD88, we found that TNFα was not secreted by the MyD88−/− macrophages following infection as should be expected given that TNFα induction is entirely TLR2- and MyD88-dependent." (PMID 20041145, 2009). "Amplification of immune responses to infection in the kidney may also occur, as the proinflammatory cytokines TNF-α and IFN-γ have been shown to induce renal expression of Tlr2 and Tlr4." (PMID 19845042, 2009). "Therefore, increased expression of Tlr2, leading to increased levels of IL-10 and increased survival of regulatory T cells, may dampen the immune response against C. albicans, even in the presence of immune infiltrates in the kidney, and allow infection to progress." (PMID 19845042, 2009). "Survival of TLR2−/− and MyD88−/− mice, however, was significantly reduced compared to B6 mice, regardless of the route of infection or the subspecies of F. tularensis." (PMID 19936231, 2009). "Based on a variety of in vitro studies, it has been suggested that TLR2, 4, and 9 are critically involved in induction of a Th1 response following infection with Mtb however, in vivo data are not as clear cut." (PMID 19636364, 2009). "To determine if hepcidin could be expressed independent of TLR4 activation, we measured serum hepcidin levels in C3H/HeJ mice (TLR2+/+, TLR4-/-) and compared the values to C3H/HeSnJ mice (TLR2+/+, TLR4+/+) after infection with M. arthritidis." (PMID 19930711, 2009). "Thus, we intranasally inoculated TLR2 KO and WT mice with S. pneumoniae D39 or S. pneumoniae PLN and evaluated their response to the infection 6 h later." (PMID 17711480, 2008). "In addition to the role of TLR2 in infections with CMV, TLR2 is activated in response to Varicella Zoster virus (VZV) and it seems to play significant role in infections with HSV1." (PMID 19088911, 2008). "Both strains were found to up-regulate multiple TLRs (TLR2, 7 and 9) following the TMEV infection." (PMID 19094215, 2008). "Indeed, different effects of TLR2 and TLR4 were found in both infection models as in tissue injury models." (PMID 18974879, 2008). "We previously showed that TLR2 KO mice are indistinguishable from WT mice with regard to bacterial outgrowth and mortality after intranasal infection with a serotype 3 S." (PMID 17711480, 2008). "To further evaluate the role of TLR2 and TLR4 in the systemic inflammatory response after infection with B. pseudomallei, we semiquantitatively scored spleen histology slides generated from infected mice and performed routine clinical chemistry to evaluate hepatic and renal injury." (PMID 17676990, 2007).
infection (continued). "In order to study the extent and kinetics of the inflammatory response, we sacrificed WT, TLR2 KO, and TLR4 KO mice at multiple time points after infection and measured the concentrations of the proinflammatory cytokines TNFα and IL6 and the anti-inflammatory cytokine IL10 in lung homogenates." (PMID 17676990, 2007). "In line with these in vivo observations, we demonstrated that purified LPS from B. pseudomallei 1026b (the strain also used in the in vivo infection studies) activates HEK293 cells via TLR2, not via TLR4." (PMID 17676990, 2007). "Expression analysis of downstream genes indicate that patterns of TLR2-dependent gene regulation differ between the two NTM species and show that the presence or absence of the microbiome differentially influences specific transcriptional responses to infection." (PMID 42212334, 2026). "We found that TLR2, TLR4, TLR9, and the TLR3/4 adaptor molecule TRIF are dispensable for inducing host resistance against the subsequent infection, as observed by reduced bacterial loads in the lung of mice that were first infected with Lp thyA L. pneumophila compared to mock." (PMID 40558085, 2025). "The results revealed distinct temporal expression profiles of Toll-like receptors (TLRs), showing that TLR2, TLR4, TLR7 and TLR10 were significantly upregulated in a parabolic pattern, with TLR2 and TLR10 peaking at 36 h while TLR4 and TLR7 reached maximum expression at 24 h post-infection." (PMID 41305370, 2025). "Moreover, in the absence of NTHi infection, neither TLR2 nor TLR4 inhibitors had an effect on TNFα expression in MDMs." (PMID 40013145, 2025). "Additionally, we identified a significant increase in the TLR2 and TLR7 mRNA levels, along with activation of NF-kB-complex during the eclipse period of infection, suggesting an essential role of those TLRs in sensing DENV-ssRNA and/or structural PAMPs in viral particles by macrophages." (PMID 40934228, 2025). "pullorum infection significantly elevated (p < 0.05) the renal (CREA, UREA), hepatic (ALT, AST), immunological (IgG, IgM), and inflammatory (TNF-α, IL-6, SAA, CRP) parameters, as well as the expression of trefoil factor 3, Toll-like receptor 2, TNF-α, IL-1β, and IL-6." (PMID 41597538, 2025). "Similar to the infection studies, there was negligible secretion of proinflammatory cytokines by ΔTLR2 and ΔMyd88 cells, confirming that PE18 and PPE26 elicit production of proinflammatory cytokines by murine macrophages mediated by the innate immune receptor TLR2 and adapter Myd88." (PMID 39949767, 2025). "In addition to TLR2 involvement, TLR4 involvement was also observed during the infection." (PMID 39729468, 2024). "Moreover, infection with S. aureus reportedly elevates IL-22–derived γδ T cells in mechanically injured skin, and these cells have been identified as protective against S. aureus reinfection by producing TNF-α and IFN-γ via the TLR2/MyD88 signaling pathway." (PMID 38319737, 2024). "However, several other TLR2 ligands had no antiviral activity, suggesting that TLR2 stimulation is not sufficient to inhibit infection." (PMID 38935789, 2024). "Upon infection with Brucella or in response to Brucella lipoproteins, such as the lipidated outer membrane protein 19 (L-Omp19), macrophages release inflammatory mediators such as TNF-a, interleukin-6 (IL-6), and IL-1β in a toll-like receptor 2-dependent manner (TLR2)." (PMID 38276100, 2024). "In addition, the recombinant LRR38 encoded by LSS_01692 interacted with fibronectin, collagen IV, and Toll-like receptor 2 (TLR2); furthermore, rLRR38 induced inflammation involving the NF-κB and MAPK signal transduction pathways, suggesting its participation during infection." (PMID 39735260, 2024). "The findings that resistance to Leishmania is dependent on parasite lipophosphoglycan (LPG) by TLR-2, the generation of IL-12, and the establishment of a Th1 immune response in addition to NO production have validated the significance of TLR-2 in infection control." (PMID 37111420, 2023).
infection (continued). "Finally, looking at the fold change with respect to infection, we did not see any change in the levels of sialic acid on IgG depending on age and TLR2." (PMID 37258615, 2023). "Our findings showed that supplementing the rabbits with TQN significantly (p < 0.05) upregulated the transcription levels of IL-10, TLR-4, DEFB1 and TLR-2 genes comparing with the control non-supplemented rabbits at 96 h post-infection with P. multocida strain." (PMID 38292130, 2023). "TLR2 plays the regulatory role in IgG but not IgM response to infection." (PMID 37258615, 2023). "A previous study has reported that Ictalurus punctatus TLR2 transcripts increased in the spleen after Ichthyophthirius multifiliis infection, but its TLR9 transcripts decreased in the spleen after I. multifiliis infection, demonstrating discrepant roles of TLR2 and TLR9 against pathogens infection." (PMID 38003793, 2023). "Importantly, it was also observed that in the absence of TLR2 and the resulting IL-10, neonatal neutrophils were able to migrate to infected lungs and control infection." (PMID 37375099, 2023). "The authors also show that the earliest TLR2-dependent transcriptional responses observed in in vitro cultivated macrophages are conserved in vivo and that a lack of TLR2 in mice impacts the quantity and phenotype of cellular subsets that emerge post-infection." (PMID 37787569, 2023). "In addition, the activation of TLR2 and TLR4 in CD34+ cells and megakaryocytes in the presence of TPO may warrant platelet provision during infection episodes by an autocrine IL-6 loop triggered by the PI3K/NF-κB axes." (PMID 36674552, 2023). "However, IgM levels after infection were the same as before infection in aged mice irrespective of TLR2 expression." (PMID 37258615, 2023). "However, blocking the TLR2 signal with a neutralizing antibody (polyclonal anti-hTLR2 antibody, h-TLR2) against TLR2 before H37Ra infection did not promote the expression of PPARγ." (PMID 35432274, 2022). "Our observations suggested colocalization (yellow) between TLR2 and Nogo-B after HCMV exposure; and that TLR2 and Nogo-B cellular localisation was influenced by IFITM3, with more TLR2/Nogo-B localisation visible as cytoplasmic puncta in IFITM3−/− iPS-DCs 24 h post infection." (PMID 36075894, 2022). "However, TLR2‐/‐ mice present no free amastigotes and a reduced number of parasitized macrophages along with neutropenia during the infection period as opposed to what was observed in C57BL/6 mice." (PMID 35119120, 2022). "However, Tlr2 has a function in the migration speed of macrophages and neutrophils to infection sites with M. marinum that is not observed with M. avium." (PMID 36741407, 2022). "TLR2-dependent inflammation can be induced by the E protein of SARS-CoV-2, which may provide activation and activation signals for NLRP3 inflammasome assembly, thus promoting the release of proinflammatory cytokines such as IL-1β to deal with infection." (PMID 36389144, 2022). "Furthermore, in a S. aureus craniotomy biofilm infection model, TLR2, but not TLR9, was critical for host bacterial containment through the caspase-1-mediated activation of IL-1β, which was reduced in the Tlr2−/− mice." (PMID 36226943, 2022). "In summary, this study demonstrated that TLR2 was required for the accumulation of mtROS after C. pneumoniae infection and highlighted the activation of JunB-Fra-1 by mtROS to promote the expression of MMP2 in the infection-induced VSMC migration and atherosclerotic lesion formation." (PMID 35493076, 2022). "In this study, we investigate the role of TLR2 and TLR9 signaling in the specific context of posttraumatic S. aureus osteomyelitis with a focus on understanding how these immune receptors influence host antibacterial defenses and modulate infection-induced changes to bone homeostasis." (PMID 36226943, 2022).